APOL3 (apolipoprotein L3)
Description:
May affect the movement of lipids in the cytoplasm or allow the binding of lipids to organelles.
Synonyms: ApoL-III; CG12_1; CG12-1; APOLIII; CG121
Tractability: Antibody: its Gene Ontology location is reachable by antibodies, with medium confidence. PROTAC: ubiquitination databases record sites on it; its protein half-life has been measured.
Gene: Protein-coding gene on chromosome 22 (36,139,792 to 36,166,177, reverse strand). Ensembl gene ENSG00000128284.
Subcellular location: Cytoplasm
Gene Ontology:
Molecular function: lipid binding; lipid transporter activity
Biological process: positive regulation of canonical NF-kappaB signal transduction; inflammatory response; lipid transport; lipoprotein metabolic process
Cellular component: membrane; cytoplasm; extracellular region
Genetic constraint (gnomAD): Loss-of-function variants: 14 observed, 12.1 expected, observed/expected ratio (o/e) 1.16, 90% interval 0.76 to 1.75. The upper end of that interval is the gene's LOEUF score, 1.75, which puts it in group 6 of 6, group 1 being the genes least tolerant of losing a copy. Missense variants: 366 observed, 407.32 expected, observed/expected ratio (o/e) 0.9, 90% interval 0.82 to 0.98. Synonymous variants: 153 observed, 155.8 expected, observed/expected ratio (o/e) 0.98, 90% interval 0.86 to 1.12.
Homologues: Orthologues: chimpanzee APOL3 (95% identical), rat Apol3l1 (46% identical), rat LOC120093819 (46% identical), mouse Apol11a (40% identical), mouse Apol9b (39% identical), mouse Apol9a (39% identical), mouse Apol10b (38% identical), rat Apol9a (37% identical), mouse Apol11b (37% identical), mouse Apol10a (34% identical), zebrafish apol (25% identical), Caenorhabditis elegans F07F6.8 (14% identical), and 1 more. Paralogues in human: APOL4 (59% identical), APOL2 (53% identical), APOL1 (48% identical), APOL6 (32% identical), APOL5 (29% identical), APOLD1 (16% identical).